TBX2 (T-box transcription factor 2)
Diseases named in the same sentence as TBX2 in open-access papers (continued):
Sharing a sentence is not in itself a finding about the gene and the disease.
melanoma (continued). "This conclusion was strengthened by examining individual melanoma tumors that indicated that TBX2 protein expression is highly variable between tumors and that TBX2 mRNA levels vary significantly between individual tumors in the TCGA melanoma cohort (black line)." (PMID 34819350, 2021). "In agreement, TBX2 expression followed closely that of PAX3 in human melanomas." (PMID 34819350, 2021). "In contrast, by using high-affinity anti-HA antibody and HA-tagged endogenous Tbx2 in melanoma, we were able to identify up to 7500 binding sites (clone 9, R2) with a robust set of sites identified in common between multiple replicates, of which ∼38% were within 3 kb of the transcription start site." (PMID 34819350, 2021). "The knockdown of TBX2 in 501mel melanoma cells increased their sensitivity to CA5 by up to 5 times." (PMID 32195221, 2020). "Genes encoding acid phosphatase 5 (ACP5), a transport protein recently recognized as a prognostic biomarker in primary melanomas, and T-box 2 (TBX2), a transcription factor that is crucial in embryonic development and in suppressing senescence in melanoma, were also up-regulated in melanospheres." (PMID 24733089, 2014). "TBX2 was also shown to bind to and repress the p21WAF1 promoter both in vitro and in vivo and to have a role in maintaining proliferation and suppressing cell senescence in melanoma cells." (PMID 24742492, 2014). "However, evidence has been provided that an Rb/p16 independent mechanism via inactivation of T-box transcription factor Tbx2, which is overexpressed in melanomas, can also lead to melanoma cell senescence." (PMID 19642975, 2009). "Moreover, both TBX2 and TBX3 show anti-senescence properties, while a dominant negative form of Tbx2 can induce senescence in a melanoma cell line." (PMID 17173667, 2006). "Interestingly, while highly homologous, in cancers where they are both overexpressed, such as melanoma, TBX2 and TBX3 have central but distinct roles where TBX2 functions as a potent growth promoting factor and TBX3 contributes to tumour formation and invasion." (PMID 39403898, 2024). "Therefore, it seems likely that the effects of PI3K signaling on melanoma growth, progression, and senescence bypass may be mediated at least in part by TBX2." (PMID 34819350, 2021). "To determine whether TBX2 in human tumors was likely to perform a similar role, we performed GSEA on the TCGA melanoma cohort ranked according to TBX2 expression and asked which gene sets were enriched in the 50 highest TBX2-expressing tumors compared with the 50 lowest." (PMID 34819350, 2021). "Niclosamide, piroctone olamine and pyrvinium pamoate were identified as ‘hit’ drugs that exhibit cytotoxicity in melanoma and RMS through their ability to target TBX2 and TBX3." (PMID 39912718, 2025). "PO was previously identified as a TBX2‐ and TBX3‐targeting drug in TBX2 and TBX3 dependent melanoma and rhabdomyosarcoma cells." (PMID 40717225, 2025). "This study shows that niclosamide, piroctone olamine and pyrvinium pamoate downregulate TBX2 and TBX3 in 501mel melanoma cells and RD ERMS cells and downregulate TBX2 in RH30 ARMS cells with negligible effects on TBX3 levels." (PMID 39403898, 2024). "“Hit” drugs were validated for their effect on TBX2/TBX3 levels and cytotoxicity in TBX2/TBX3‐dependent melanoma and rhabdomyosarcoma cells." (PMID 39403898, 2024). "At the transcriptional level, MITF controls genes involved in cell survival (BCL2, HIF1A, BCL2A1), migration (DIAPH1, MET) and proliferation (CDK2, TBX2, CDKN1B), providing important signals for growth of melanoma cells." (PMID 34289891, 2021). "Using melanoma as a model, they show that TBX2 lies downstream from PI3K signaling and that TBX2 binds and is required for expression of E2F1, a key antisenescence cell cycle regulator." (PMID 34819350, 2021).
melanoma (continued). "Here, siRNA knockdown of TBX2 in two NPC cell lines significantly decreased cancer cell proliferation, which was consistent with previous studies in heart cells, in melanoma cells and rhabdomyosarcoma cells." (PMID 28881763, 2017). "Although TBX2 and TBX3 share many properties at the molecular and cell biological level, they can be functionally distinct, at least in melanoma cells." (PMID 26579496, 2015). "The two closely related T-box transcription factors TBX2 and TBX3 are considered oncogenes because they are frequently overexpressed in melanoma and various types of human cancer, such as breast, bladder, liver, and pancreas carcinoma." (PMID 26579496, 2015). "T-box genes/proteins such as TBX2 and TBX3 are overexpressed in several neoplasms, including melanomas, breast, and pancreatic cancer." (PMID 22829758, 2012). "MiTF also controls the expression of Tbx2 and CDK2, which are involved in melanoma proliferation and suppression of senescence, in addition to anti-apoptotic genes such as Bcl2 and ML-IAP." (PMID 20174581, 2010). "Interestingly, niclosamide, piroctone olamine and pyrvinium pamoate inhibit the Wnt/β-catenin pathway and were recently shown to inhibit TBX2 and TBX3 levels and to exert anti-cancer activity in TBX2/3-driven melanoma and rhabdomyosarcoma." (PMID 39912718, 2025). "The highly homologous T‐box transcription factors TBX2 and TBX3 are critical for embryonic development, and their overexpression in postnatal tissues contributes to a wide range of malignancies, including melanoma and rhabdomyosarcoma." (PMID 39403898, 2024). "Indeed, these ‘hit’ drugs were shown to display potent cytotoxicity in melanoma and RMS cells and therefore have the potential to be repurposed for the treatment of TBX2/3‐driven cancers." (PMID 39403898, 2024). "This study shows for the first time that niclosamide, piroctone olamine and pyrvinium pamoate can negatively regulate the oncogenic TBX2 and TBX3, and it also broadens the anti‐cancer activity of these drugs to include efficacy against melanoma and rhabdomyosarcoma." (PMID 39403898, 2024). "Interestingly, TBX2 and the closely related TBX3 gene are reactivated and/or overexpressed in several cancers including small cell lung carcinoma melanoma, breast, pancreatic, liver, and bladder cancers." (PMID 33731112, 2021). "In contrast, in cells treated with the Tbx2-specific siRNA Tbx2 expression was extinguished in almost all cells examined whereas Cdkn1b expression was strongly upregulated in the cytoplasm (in MCF-7 cells) and in the nucleus (in B16 melanoma cells)." (PMID 23341776, 2013).
neuroblastoma (14 papers, 2019 to 2025). Neuroblastoma (NB) is the most common solid, extracranial childhood tumor. "Increased expression of CHGA, GATA2, and TBX2 was observed with STM2457 treatment in the neuroblastoma xenografts." (PMID 38691450, 2024). "This was addressed in silico through comparison of our MCF7 data with publicly available TBX2 ChIP-seq in N-Myc amplified neuroblastoma, the only other known cancer in which TBX2 ChIP-seq has been performed to date." (PMID 35687133, 2022). "This is consistent with a previous study in which Tbx2 ChIP-seq from neuroblastoma cells identified only 557 significant bound sites (q < 0.05)." (PMID 34819350, 2021). "Furthermore, neuroblastoma patient-derived organoids have been incorporated into a study identifying the gene TBX2 as a component of the neuroblastoma core transcriptional regulatory drive." (PMID 33808071, 2021). "Furthermore, TBX2 acts as a neuroblastoma core regulatory circuitry component that promotes MYCN/FOXM1-mediated reactivation of DREAM targets, while CLOCK genes are closely associated with cancer development, particularly in endocrine tissues." (PMID 32391054, 2020). "Gene expression levels for the adrenergic neuroblastoma CRC members—MYCN, HAND2, ISL1, PHOX2B, GATA3, ASCL1, and TBX2—were assayed by quantitative RT-PCR at 1, 3, and 6 days after treatment with 5 μM ATRA." (PMID 34669465, 2021). "The adrenergic CRC consists of an interdependent autoregulatory network that includes HAND2, ISL1, PHOX2B, GATA3, ASCL1, and TBX2 and is essential to drive the expression of MYCN and to facilitate the growth and survival of MYCN-amplified neuroblastoma cells." (PMID 34669465, 2021). "For example, in MYCN-amplified neuroblastoma, the TFs MYCN, HAND2, ISL1, PHOX2B, GATA3, and TBX2 are essential for maintaining cell state and survival." (PMID 34712617, 2021). "Regulatory elements controlling ASCL1 expression are bound by LMO1, MYCN and the transcription factors GATA3, HAND2, PHOX2B, TBX2 and ISL1—all members of the adrenergic (ADRN) neuroblastoma core regulatory circuitry (CRC)." (PMID 31819055, 2019). "Indeed, MYCN, ISL1, HAND2, and PHOX2B, together with GATA3 and TBX2, comprise the core regulatory circuit, an autoregulatory transcriptional loop that maintains the malignant phenotype of MYCN-positive neuroblastoma." (PMID 37297004, 2023). "Thus, ATRA initiates a change in cell state of neuroblastoma cells corresponding to a shift from the adrenergic CRC to a new retino-sympathetic CRC, which includes RARA, HAND2, ISL1, TBX2, TBX3, MEIS1, and SOX4." (PMID 34669465, 2021). "In addition, LMO1 occupancy was associated with enrichment of transcription factors that have previously been shown as members of the ADRN neuroblastoma CRC, including PHOX2B, HAND2, TBX2, and ISL15,19–21 (left)." (PMID 31819055, 2019). "This variant was found to be located in open chromatin regions identified in 29 ATAC‐seq and 5 H3K27ac ChIP‐seq experiments in various neuroblastoma cell lines, but also showed the highest enrichment of TF binding sites, including MYCN, LMO1, GATA3, HAND2, ISL1, PHOX2B, and TBX2." (PMID 40525640, 2025). "Neuroblastoma derives from embryonic neural crest cells, and in NB tumors that harbor amplification of the proto-oncogene MYCN, a transcriptional core regulatory circuitry (CRC) that includes MYCN, HAND2, ISL1, PHOX2B, GATA3, and TBX2 promotes tumorigenesis." (PMID 40766465, 2025).
breast tumor (10 papers, 2012 to 2024). "Here, we demonstrate a previously unknown mechanism of TBX2-mediated gene repression in breast tumours, whereby TBX2 physically interacts with CoREST-associated proteins LSD1, HDAC1 and the ZNF217 oncogene." (PMID 35687133, 2022). "Previous studies have found that GC and breast tumors patients with high TBX2 expression levels exhibit a worse prognosis than those with low TBX2 expression." (PMID 38965548, 2024). "Overall, these data indicate that inhibition of CoREST proteins represents a promising therapeutic intervention for TBX2-addicted breast tumours." (PMID 35687133, 2022). "In this study we show for the first time that the putative breast tumor suppressor gene CST6 is consistently repressed by the oncogenic transcription factor TBX2 through a mechanism involving EGR1." (PMID 24742492, 2014). "It was perhaps surprising that TBX2 expression was predictive of poor prognosis but independent of ER status and that basal subtype and high-grade breast tumors had slightly lower average levels of TBX2 expression." (PMID 22844464, 2012). "Since little is known about TBX2 expression in human breast tumors, we performed a comprehensive meta-analysis of TBX2 expression using an integrated gene expression database that encompassed 1107 primary human breast tumors from six published datasets." (PMID 22844464, 2012). "Overall these data highlight a novel therapeutic opportunity whereby poor-prognosis, TBX2-overexpressing breast tumours may be pharmacologically exploited by targeting the CoREST-dependent gene repression network, to recover normal growth control." (PMID 35687133, 2022). "The TBX2 gene is located on 17q23 and is often over-expressed in this breast tumour subset." (PMID 35687133, 2022). "In this study, we have identified the embryonic transcriptional repressor and anti-senescence factor TBX2 as a novel potent inducer of EMT that directly represses E-cadherin transcription and promotes an aggressive, mesenchymal breast tumor phenotype." (PMID 22844464, 2012). "Together these results inferred that the interaction and coordinated activity between TBX2 and CoREST proteins LSD1, ZNF217 and HDAC1 may be essential for repression of TSGs to promote breast tumour survival." (PMID 35687133, 2022). "This could suggest that efficient repression of E-cadherin by TBX2 might require cooperation with other transcriptional repressors that may not be present in all TBX2-overexpressing breast tumor cell lines." (PMID 22844464, 2012). "Located within the inactive TADs, five of the six aforementioned non-ATC loci (except EFCAB3) were highly methylated at shore regions of CpG island promoters (i.e., TBX2, TBX4, MRC2, and MARCH10) and non-CpG island promoter (i.e., NACA2) in 77 breast tumors compared to 10 normal controls (ref. #)." (PMID 32408897, 2020).
prostate carcinoma (9 papers, 2018 to 2025). A carcinoma that arises from epithelial cells of the prostate gland. "(2017) showed that Wnt signalling is an essential mediator of TBX2 in prostate cancer metastasis and that blocking the pathway through neutralising antibodies or a Wnt antagonist blocked TBX2‐induced invasion in prostate cancer cells." (PMID 39403898, 2024). "It was also reported that the overexpression of TBX2 in prostate cancer was correlated with pathological grade and tumor stage and might act as a potential cancer marker in prostate cancer." (PMID 38413457, 2024). "Blocking TBX2 reduced bone metastases and tumor growth in mouse prostate cancer xenograft models." (PMID 29380085, 2018). "It is tempting to speculate that the ability of these drugs to inhibit TBX2 and TBX3 may be through their inhibition of the Wnt signalling pathway because it has been previously reported to regulate TBX2 in pancreatic and prostate cancer and TBX3 in liver cancer." (PMID 39403898, 2024). "Besides, TBX2 had been reported to play a role in bone metastasis in prostate cancer." (PMID 31897234, 2020). "PIK3R5, TBX2 and TWIST1 gene were found to be hypermethylated in all four cancers, while CDKN2A (ARF) is hypermethylated in colorectal and prostate cancers." (PMID 33143142, 2020). "Firstly, through literature searching, we found TBX2 has been proposed to be a novel therapeutic target and as an upstream of WNT3A in metastasis for skeletal complications in patients of prostate cancer." (PMID 31897234, 2020). "TBX2 is a transcription factor that is overexpressed in bone metastases of CRPC, which acts through the WNT signaling pathway shown to be involved in prostate cancer progression and bone metastases." (PMID 29380085, 2018). "In addition, it has been recently underscored as a novel therapeutic biomarker in bone metastasis in prostate cancer 46, but so far, the key role of TBX2 in bone metastasis of LAC had never been understood." (PMID 31897234, 2020).
rhabdomyosarcoma (9 papers, 2017 to 2025). A rare aggressive malignant mesenchymal neoplasm arising from skeletal muscle. "The expression of TBX2 was shown to block muscle cell differentiation and to promote proliferation of rhabdomyosarcoma cells." (PMID 29542868, 2018). "Recent work has shown that TBX2 is a central component of the PTEN/PI3K/AKT signaling pathway in rhabdomyosarcoma cells by repressing PTEN." (PMID 28881763, 2017). "We also hypothesised that the ‘hit’ drugs may inhibit endogenous TBX2 and/or TBX3 in other TBX2/3‐driven cancers including rhabdomyosarcoma (RMS)." (PMID 39403898, 2024). "TBX2 recruits HDAC1 and interacts with myogenic regulators MyoD and myogenin, promoting rhabdomyosarcoma cell proliferation by inhibiting p21." (PMID 38965548, 2024). "We have shown that TBX2 represses p21, p14/19, and PTEN in rhabdomyosarcoma (RMS) and skeletal muscle but the function and regulation of TBX3 were unclear." (PMID 30979887, 2019).
lung carcinoma (6 papers, 2018 to 2024). "Nevertheless, our research suggested that the expression of TBX2 was significantly downregulated in lung cancer, which was supported by Khalil’s study." (PMID 38413457, 2024). "The Kaplan–Meier curve and log-rank test analysis suggested that subfamily members of TBX2 are all correlated with overall survival (OS) of lung cancer patients (logrank P < 0.05)." (PMID 38413457, 2024). "We also evaluated first progression (FP) of 982 patients with lung cancer using Kaplan-Meier plot for TBX2." (PMID 31897234, 2020). "To determine whether the upregulation of TBX2 was a common event, we extended our analysis in a number of human lung cancer microarray data sets using Oncomine." (PMID 31897234, 2020). "Therefore, we were interested if TBX2 was played similar functional role in bone metastasis of lung cancer." (PMID 31897234, 2020). "Thus, based on this, our initial hypothesis is that TBX2 may also regulate WNT pathway during the progression of lung cancer." (PMID 31897234, 2020). "This was corroborated by the identification of methylation-regulated genes (PCDH10, TBX2, and CDO1) recently described as biomarkers in localized lung cancers and premalignant lesions." (PMID 36461127, 2022). "Our current study showed that TBX2 had detectable expression in LAC cell lines and in a number of human lung cancer microarray data sets." (PMID 31897234, 2020). "Western blots using up to 25 μg of nuclear extracts showed very little or undetected expression of TBX2, TBX3, and TBX5 in all tested lung cancer cell lines while only HBEC2 cells expressed TBX5 which is consistent with qPCR results." (PMID 30425966, 2018). "Moreover, lung cancer patients with elevated expression of TCF21, NKX2-1, TBX2, and TBX5 exhibited a decreased rate of survival relative to patients with low gene expression." (PMID 37627195, 2023). "Interestingly, PCDH10, TBX2, and CDO1 were described as potential biomarkers for early-stage lung cancers." (PMID 36461127, 2022). "We found that cell proliferation in TBX2 siRNA group was much weaker compared with the negative control group in both two cell lines, indicating TBX2 might play a key regulator in cell proliferation of lung cancer." (PMID 31897234, 2020). "E xpression of the hub genes HBEGF, GJA4, DDR1, CD24, TBX2, GATA3, and SASH1 did not appear to be prognostic in lung cancer." (PMID 37324026, 2023).
pancreatic cancer (6 papers, 2006 to 2025). "Regarding the relationships of each subfamily of T-box gene and cancer, TBX2 and TBX3 over-expressions were observed in several human cancers, including ovarian, cervical, mammary, liver and pancreatic carcinomas, and current findings revealed its association with malignant behavior." (PMID 33447348, 2020).
glioblastoma (5 papers, 2016 to 2025). The most malignant astrocytic tumor (WHO grade IV). "Examination of the PPI interaction networks suggests that the ion channel CFTR, the phospholipase PLCB1, and the transcription factor TBX2 ought to be considered novel potential proteins to be inhibited for the treatment of glioblastoma." (PMID 27564115, 2016). "Indeed, TBX2 expression correlates with poor prognosis in glioblastoma (GBM) and CRC; invasion and metastasis in lung, breast, pancreatic, prostate, nasopharyngeal, gastric and CRC; tumour recurrence in gastric cancer; and lymph node metastasis in cervical cancer and endometrial adenocarcinoma." (PMID 39912718, 2025). "PPI and gene ontology networks examined suggest the existence of further targets to be explored for the treatment of glioblastoma, such as PRKG1, CFTR, PLCB1, and TBX2." (PMID 27564115, 2016).